AKT1 (AKT serine/threonine kinase 1)
Diseases named in the same sentence as AKT1 in open-access papers (continued):
Sharing a sentence is not in itself a finding about the gene and the disease.
lipid metabolism disorders (10 papers, 2021 to 2025). "Considering that AKT1-deficient adipocytes are less sensitive to insulin, menopause may thus interfere with lipid storage, leading to lipid metabolism disorders." (PMID 35707470, 2022). "These targets play an important role in the PPI network and KEGG signaling pathway, and they have a significant impact on glucose, lipid metabolism disorders, and inflammation (such as TNF-α, AKT1, PPARG, and PTGS2)." (PMID 36199550, 2022). "These targets play an important role in the PPI network and KEGG signaling pathway, and they have a significant impact on glucose and lipid metabolism disorders and inflammation (such as TNF-α, AKT1, PPARG, and PTGS2)." (PMID 36199550, 2022).
Nephropathy (10 papers, 2019 to 2025). A nonspecific term referring to disease or damage of the kidneys. "Moreover, the expression of JAK1, AKT1, and NF-κB was significantly increased in the model group, and there was low expression in the Nephropathy 1st group." (PMID 36339588, 2022).
cerebral infarction (9 papers, 2016 to 2025). An ischemic condition of the brain, producing a persistent focal neurological deficit in the area of distribution of the cerebral arteries. "The potential medicinal ingredients of ZTC mainly act on core targets such as ALB, AKT1, and IL-6, and then regulate related molecular pathways to achieve the effect of treating or delaying cerebral infarction." (PMID 35047043, 2022).
Cowden syndrome (9 papers, 2019 to 2024). "The phenotypes related to PTEN variants are, as expected, similar to AKT1, including Cowden syndrome and hereditary breast and ovarian cancer syndrome." (PMID 32858845, 2020). "Several genes, such as EGRF, SDHB-D, PIK3CA/AKT1, and PTEN, have been linked to Cowden syndrome." (PMID 39686423, 2024). "In approximately 10% of Cowden syndrome patients, the PTEN variant is absent; instead, the presence of germinal variants is detected in AKT1 (14q32.33) or PIK3CA, i.e., the genes actively involved in the same PI3K/AKT signalling pathway that is inhibited by PTEN." (PMID 35743146, 2022).
cutaneous melanoma (9 papers, 2014 to 2025). A primary melanoma arising from atypical melanocytes in the skin. "In this study, the nuclear p-Akt1 expression was associated with the presence of distant metastasis in patients with cutaneous melanomas." (PMID 30647870, 2018). "Our results also showed that p-Akt1 expression was significantly higher in sinonasal melanomas than in oral and cutaneous melanomas." (PMID 30647870, 2018). "Oral melanomas have scores of p-Akt1-positivity (mean = 19.45%, ranging from 2.6% to 44.4%) similar to the cutaneous melanomas with metastatic history." (PMID 30647870, 2018). "Although a correlation between p-Akt1 expression and the metastatic status in cutaneous melanomas have been found for these tumours, the p-Akt1 showed prognostic values only in the univariate model, but it was lost in the multivariate model." (PMID 30647870, 2018). "One previous study shows the putative role of p-Akt1 in metastatic cutaneous melanomas." (PMID 30647870, 2018). "The p-Akt1 expression was predominantly detected in the nucleus, and non-metastatic cutaneous melanomas have a mean of 5.6% of the nuclei positive (ranging from 0% to 50.15%)." (PMID 30647870, 2018). "We also compared the scores of p-Akt1-positive nuclei into four groups: (a) primary (cutaneous melanoma) without metastatic history; and (b) primary (cutaneous melanoma) with metastatic history, (c) oral melanomas, and (d) sinonasal melanomas." (PMID 30647870, 2018).
lung squamous cell carcinoma (9 papers, 2015 to 2026). "We finally exemplified an 82-year-old patient with advanced lung squamous cell carcinoma in our center, who had AKT1 mutation in the tumor and good response to pembrolizumab." (PMID 35642038, 2022). "In the case of lung squamous cell carcinoma, the curves for different expressions in 3 key targets appeared to separate, particularly for AKT1." (PMID 36654811, 2023). "Our results suggest that it is most likely to indicate the occurrence of NRAS, AKT1 and PTEN mutations in metastatic sites of squamous cell lung carcinoma." (PMID 28097440, 2017).
overgrowth syndrome (9 papers, 2017 to 2025). A group of syndromes caused by genetic birth defects that may lead to the development of malignancies. "Then, mosaicisms were recognized as other causative mechanisms of overgrowth syndromes, and several of the genes involved, including AKT1, PTEN, and PIK3CA, have been identified." (PMID 32778138, 2020).
pneumonia (9 papers, 2014 to 2025). An acute, acute and chronic, or chronic inflammation focally or diffusely affecting the lung parenchyma, caused by an infection in one or both of the lungs (by bacteria, viruses, fungi, or mycoplasma.). "Vagal α7nAChR signaling regulates α7nAChR+Sca1+VE-cadherin+ EPCs via phosphorylation of Akt1 during lung injury repair in pneumonia." (PMID 32867826, 2020). "Vagotomy reduced α7nAChR+Sca1+VE-cadherin+p-Akt1+ cells in the bone marrow and lung from pneumonia mice." (PMID 32867826, 2020). "Vagotomy could reduce α7nAChR+VE-cadherin+ and VE-cadherin+p-Akt1+ cells in the bone marrow in pneumonia." (PMID 32867826, 2020). "During pneumonia, these cells could be regulated by vagal α7nAChR signaling via phosphorylation of Akt1." (PMID 32867826, 2020). "We have provided direct evidence that Akt1 is a key regulator of EPC repair during pneumonia." (PMID 32867826, 2020). "Knockout of Akt1 could reduce Sca1+ cells in the bone marrow, blood, and BAL in pneumonia mice." (PMID 32867826, 2020).
acne (8 papers, 2017 to 2025). An inflammatory process of the sebaceous glands which is characterized by comedones, nodules, papules and/or pustules on the skin. "Based on the PPI network analysis and topology algorithm in Cytoscape software, TNF, GAPDH, IL6, Albumin (ALB), and protein kinase 1 (AKT1) are considered to be the core target proteins for the treatment of acne." (PMID 39029003, 2024).
brain injury (8 papers, 2017 to 2025). Acute and chronic (see also brain INJURIES, CHRONIC) injuries to the brain, including the cerebral hemispheres, CEREBELLUM, and brain STEM. "Furthermore, SHD promotes the level of IL-6 and APP proteins in rats after ischemic brain injury and reduces the level of AKT1 and VEGFA proteins." (PMID 35097126, 2022).
chronic obstructive pulmonary disease (8 papers, 2022 to 2026). A chronic and progressive lung disorder characterized by the loss of elasticity of the bronchial tree and the air sacs, destruction of the air sacs wall, thickening of the bronchial wall, and mucous accumulation in the bronchial tree. "A total of 379 targets related to BHC and 7391 targets related to COPD were obtained, including 313 potential targets of BHC in treating chronic obstructive pulmonary disease, with JUN, AKT1, TNF, IL6, EGFR, MAPK1, and MAPK14 as the core targets." (PMID 36523421, 2022).
Cirrhosis (8 papers, 2015 to 2025). A chronic disorder of the liver in which liver tissue becomes scarred and is partially replaced by regenerative nodules and fibrotic tissue resulting in loss of liver function. "Botanical drugs and gut microbiota target MAPK1, VEGFA, STAT3, AKT1, RELA, JUN, and ESR1 in the treatment of hepatitis B cirrhosis, and their combined use has shown promise for cirrhosis treatment." (PMID 38029250, 2023).
Ewing sarcoma (8 papers, 2005 to 2024). A small round cell tumor that lacks morphologic, immunohistochemical, and electron microscopic evidence of neuroectodermal differentiation. "Of the priority candidates, 6 were found with enriched dependency in Ewing Sarcoma cell lines (AKT1, BARD1, HSP90AA1, NCOA1, SETDB1, SMAD4)." (PMID 38177639, 2024). "For example, AKT1, is a downstream kinase of phosphoinositide 3-OH kinase and has been shown to prevent apoptosis and support survival of many cell types including Ewing's sarcoma." (PMID 20718987, 2010).
hyperuricemia (8 papers, 2016 to 2025). An abnormally high level of uric acid. "The core targets of Plantaginis Herba for the treatment of hyperuricemia were AKT1, mitogen-activated protein kinase 3 (MAPK3), MAPK1, tumor necrosis factor (TNF), prostaglandin-endoperoxide synthase 2 (PTGS2), sirtuin 1 (SIRT1), estrogen receptor 1 (ESR1), and androgen receptor (AR)." (PMID 33897800, 2021).
Infertility (8 papers, 2016 to 2026). "Further, the AKT1‐KO murine study revealed significantly fewer primordial follicles leading to infertility." (PMID 39440457, 2024). "Network pharmacology identified linoleic acid, oleic acid, biotin, and esculentic acid as key contributors to the extract's anti-infertility effects, potentially via interactions with EGFR, HIF1, BCL2, TNF, and AKT1." (PMID 42199843, 2026).
invasive ductal breast carcinoma (8 papers, 2010 to 2022). The most common type of invasive breast carcinoma, accounting for approximately 70% of breast carcinomas. "Mutations of the AKT1 gene have been reported in 1.4 to 8% (mean ~ 4%) of infiltrating ductal carcinomas." (PMID 30227836, 2018). "We then found that YB-1 knockdown also inhibits the initial generation in mice of invasive ductal carcinomas and ductal carcinomas in situ from freshly isolated human mammary cells transduced, respectively, with KRASG12D or myristoylated-AKT1." (PMID 34294889, 2022).
mastitis (8 papers, 2018 to 2025). Inflammation of breast tissue during lactation or postpartum due to an obstructed duct or infection. "This intervention not only reactivates AKT1 expression and its downstream mTOR pathway, but also restores milk protein synthesis, directly alleviating mastitis symptoms." (PMID 40711322, 2025). "SYK and PTK2B may be involved in the SYK/PTK2B/AKT1/JAK2 pathway in bMECs that stimulates IL-8 secretion and recruits neutrophils to kill pathogenic microorganisms, resulting in the resistance to mastitis inflammation." (PMID 31447828, 2019).
premature ovarian failure (8 papers, 2020 to 2026). "It has been reported that AKT1 plays an essential role in regulating ovarian growth and maturation and that AKT1 deficiency leads to premature ovarian failure in female mice." (PMID 39568012, 2024).
Salmonella Infections (8 papers, 2014 to 2022). Infections with bacteria of the genus SALMONELLA. "Using this atlas, we identified essential mediators of stem cell differentiation, modulators of Salmonella infection, and new targets of AKT1." (PMID 27909043, 2016).
tongue cancer (8 papers, 2019 to 2025). A malignant neoplasm affecting the tongue. "Further mechanistic studies are required to elucidate the role of MAPK1 and AKT1 in treatment resistance of tongue cancer." (PMID 36393868, 2022). "Evidence indicates that in tongue cancer cells, FAM168A, also known as tongue cancer resistance-associated protein (TCRP1), can directly bind to AKT1 and regulate AKT1/NFκB signaling pathways." (PMID 31291942, 2019). "Thus, it might be possible that out of all three isoforms, only Akt1 and 2 play a key role in tongue cancer development." (PMID 31252679, 2019). "Our results suggest MAPK1, AKT1, and MAPK3 as potential drug targets in NACT resistant tongue cancer patients." (PMID 36393868, 2022). "In RPPA, protein expression of 61 tongue cancer patients were available and the expression of only the top two kinases (MAPK1 and AKT1) are reported in these patients." (PMID 36393868, 2022). "Due to the lack of data on NACT response on tongue cancer in public databases, it limits to draw conclusive correlation on MAPK1 and AKT1 expression with treatment resistance." (PMID 36393868, 2022).
tuberculosis (8 papers, 2017 to 2024). A chronic, recurrent infection caused by the bacterium Mycobacterium tuberculosis.
acute promyelocytic leukemia (7 papers, 2011 to 2025). An aggressive form of acute myeloid leukemia (AML), characterized by arrest of leukocyte differentiation at the promyelocyte stage, due to a specific chromosomal translocation t(15;17) in myeloid cells. "As a chemotherapy drug for acute promyelocytic leukemia (APL), arsenic trioxide has been reported to decrease the activity of a serine/threonine-protein kinase AKT1." (PMID 31125330, 2019).
anemia (7 papers, 2012 to 2025). A reduction in the number of red blood cells, the amount of hemoglobin, and/or the volume of packed red blood cells. "Integrated NP and LC-MS/MS analysis revealed SYD’s molecular mechanism for anemia: active components (ferulic acid, calycosin, and astragaloside A) act on the PI3K-Akt signaling pathway via AKT1, MAPK1, and MAPK14." (PMID 40732361, 2025).
Arrhythmia (7 papers, 2018 to 2025). Any cardiac rhythm other than the normal sinus rhythm. "The expression of AKT1 increased in the aconitine arrhythmia group, while the expression of AKT1 was decreased by treatment with DHI and sotalol, a known antiarrhythmia drug." (PMID 35915792, 2022). "In the drug-ingredient-target network of DHI, Akt1 and HMOX1 are the two key gene targets of DHI against arrhythmia." (PMID 35915792, 2022). "Our cell experiments suggested that aconitine could induce arrhythmias and that DHI could rescue the abnormal expression of Akt1 and HMOX1 in aconitine-induced arrhythmias." (PMID 35915792, 2022).
Atrophy (7 papers, 2016 to 2025). Any weakening or degeneration, especially through lack of use. "Thus, AKT1 may contribute to the activity of HZJD against atrophy." (PMID 33354218, 2020).
Autoimmunity (7 papers, 2018 to 2024). The occurrence of an immune reaction against the organism's own cells or tissues. "Therefore, we speculate that the development of BBR in improving POF may be involved in regulating cell apoptosis and autoimmunity by regulating the PTEN/AKT1/FoxO1 pathway and Bim and Fas/FasL targets." (PMID 35420511, 2022).
brain cancer (7 papers, 2013 to 2025). A primary or metastatic malignant neoplasm affecting the brain. "Notably, the phosphorylated ERK1/2 and AKT1/2/3 were both up-regulated in all brain cancer cell lines measured, implicating a contributing role of these two pathways in brain carcinogenesis." (PMID 40362634, 2025).
chronic atrophic gastritis (7 papers, 2015 to 2025). Atrophic gastritis that is persistent and long-standing.
colon adenocarcinoma (7 papers, 2017 to 2024). "Similarly, AKT1 has been confirmed to have a relationship between UC and colon adenocarcinoma." (PMID 34970312, 2021). "Known Hsp90 clients EGFR, HER2, CDK4, CDK6, CXCR4, Akt-1, c-Raf, Survivin, ERK-5 and Integrin α2 were analyzed following the administration of KUNB31 to HT29 (colon adenocarcinoma grade II) cells." (PMID 29382832, 2018).
dilated cardiomyopathy (7 papers, 2013 to 2025). Cardiomyopathy which is characterized by dilation and contractile dysfunction of the left and right ventricles. "In utero echocardiography revealed abnormal blood flow patterns at the mitral valve and reduced contractile function of Akt1 null fetuses, while ex vivo μCT and histology unraveled structural alterations such as dilated cardiomyopathy and ventricular septum defects in these fetuses." (PMID 24400145, 2013).
infarction (7 papers, 2018 to 2025). A localised pathological necrosis of tissue resulting from obstruction of the blood supply usually by a thrombus, an embolus, or vascular torsion. "In the rAION model, puerarin can continuously activate Akt1, and the activation of Akt1 needs to actuate M2 polarization after infarction." (PMID 36358493, 2022). "The Akt/Nrf2 pathway plays a crucial role in promoting the angiogenic-related functions of BM-MSCs, as demonstrated during infarction, where MSCs overexpressing AKT1 are able to preserve normal pH levels in the surviving myocardium." (PMID 32215017, 2020).
inflammatory breast carcinoma (7 papers, 2017 to 2023). An advanced, invasive breast adenocarcinoma characterized by the presence of distinct changes in the overlying skin. "Furthermore, high caveolin-1 levels mediate inflammatory breast cancer (IBC) cell invasion by activating Akt1, which in turn causes RhoC GTPase phosphorylation." (PMID 31148948, 2019). "Phosphorylation of Rho-GTPase by AKT1 in inflammatory breast cancer cells is critical for promoting caveolin-1-mediated migration suggesting that AKT1 conversely promotes migration in this cellular context." (PMID 28082369, 2017). "AKT1 knock-down can also reduce the invasiveness of inflammatory breast cancer." (PMID 33291460, 2020). "Caveolin-1 was identified as a potential specific activator of AKT1 in inflammatory breast cancer." (PMID 31752925, 2019). "In inflammatory breast cancer (IBC) cells, the high expression of Cav-1 activates the Akt1 signaling pathway and phosphorylates the RhoC-GTP enzyme, thereby promoting the adhesion and migration of breast cancer cells and enhancing cell invasion." (PMID 37828916, 2023). "As a result AKT1 levels are increased and AKT2 levels are decreased in inflammatory breast cancer compared to normal breast tissue." (PMID 31752925, 2019). "Astonishingly, in inflammatory breast cancer AKT3, but not AKT1 or AKT2, increases proliferation and decreases apoptosis." (PMID 31752925, 2019).
neuroendocrine tumors (7 papers, 2016 to 2023). "To test for differentiation in AKT1 overexpressing cells, we performed immunohistochemistry for the differentiation marker Synaptophysin, which has been shown to be expressed in CNS tumors with neuronal differentiation as well as in neuroendocrine tumors." (PMID 29465400, 2018).
preeclampsia (7 papers, 2021 to 2025). Preeclampsia is a hypertensive disorder of pregnancy that is characterized by new-onset hypertension with proteinuria presenting after 20 weeks of gestation, and depending on mild or severe forms may initially present with severe headache, visual disturbances, and hyperreflexia. "Apelin and exercise increase AMPK, PGC-1α, PI3k, and AKT1 leading, to stimulation of GLUT4 and GLUT1 in pregnant rats while also stimulating eNOS/NO, increasing PlGF, decreasing sFlt-1, decreasing sEng, and reducing oxidative stress to improve preeclampsia symptoms." (PMID 37964253, 2023).